CRP (C-reactive protein)
Diseases named in the same sentence as CRP in open-access papers (continued):
Sharing a sentence is not in itself a finding about the gene and the disease.
sarcopenia (continued). "The role of C-reactive protein (CRP), an inflammatory marker, in the development of sarcopenia remains uncertain." (PMID 39502753, 2024). "MR analysis provided further evidence of a significant detrimental link between genetically predicted CRP levels and essential sarcopenia characteristics, with consistent results across various statistical models." (PMID 39502753, 2024). "Our findings revealed that elderly RCT patients with sarcopenia exhibited higher levels of CRP (3.75 ± 6.64 mg/L vs. 2.17 ± 2.30 mg/L, p = 0.021) and ESR (19.08 ± 12.86 mm/H vs. 15.95 ± 10.76 mm/H, p = 0.038) than those in the normal group." (PMID 39033299, 2024). "A cross-sectional study of 120 elderly individuals from Iran showed that blood CRP levels were significantly higher in the sarcopenia group compared to the non-sarcopenia group." (PMID 40008206, 2024). "Clinical studies conducted by others as well as our group reported that CRP levels were greater in sarcopenia patients and these studies also provide insights into a plausible connection between low-grade chronic inflammation and sarcopenia." (PMID 39186818, 2024). "Sarcopenia and a high C-reactive protein-to-albumin ratio are independent prognostic factors in patients with pancreatic cancer after pancreaticoduodenectomy." (PMID 38913646, 2024). "CRP levels were related to sarcopenia in males (OR, 1.03; 95% CI, 1–1.05) and individuals aged <50-year-old (OR, 1.03; 95% CI, 1.01–1.05), drinking (OR, 1.02; 95% CI, 1–1.03), and BMI ≥ 25 kg/m2 (OR, 1.02; 95% CI, 1–1.03)." (PMID 39969369, 2024). "Despite this, the correlation between CRP levels and sarcopenia remains to be conclusively determined." (PMID 39502753, 2024). "Compared with participates in the lowest quartile (Q1) of CRP level (Q1; ≤0.08 to ≤0.7), those in the highest quartile (Q4; ≤4.3 to ≤188.5) had an adjusted OR for sarcopenia of 2.74 (95% CI, 1.65–4.57; P < .001)." (PMID 39969369, 2024). "We initiated a case–control study by enrolling 74 sarcopenia patients and 133 nonsarcopenia patients, aiming to evaluate the significance of CRP as a stand-alone predictor for sarcopenia." (PMID 39502753, 2024). "Studies have shown that several cytokines (TNF-α, CRP, and IL-6) play an important role in the pathogenesis of sarcopenia." (PMID 38397848, 2024). "Nevertheless, the investigations exploring the correlation between CRP concentrations and sarcopenia yield diverse findings." (PMID 39502753, 2024). "It is known that, during the inflammatory process, the synthesis of acute phase proteins such as C-Reactive Protein (CRP) predominates, consequently reducing the synthesis of transthyretin (TTR), which is associated with sarcopenia." (PMID 39519615, 2024). "The CRP levels were related to sarcopenia in males, the individuals aged <50-year-old, drinking and BMI ≥ 25 kg/m2." (PMID 39969369, 2024). "Elevated levels of IL-6, IL-1β, TNF-α, and CRP have been identified as potential contributors to the unfavorable outcomes of sarcopenia in PD-1 inhibitor treatment." (PMID 39101140, 2024). "To date, there is a lack of academic literature exploring the correlation between CRP and sarcopenia through the MR method." (PMID 39502753, 2024). "Overall survival in the sarcopenia and high C-reactive protein-to-albumin ratio groups was significantly poorer than that in the non-sarcopenia and low C-reactive protein-to-albumin ratio and sarcopenia or high C-reactive protein-to-albumin ratio groups." (PMID 38913646, 2024). "Patients with sarcopenia have higher CRP levels than those healthy elderly, and inflammatory biomarkers significantly correlate with muscle damage, possibly leading to a more significant loss of muscle mass." (PMID 37685462, 2023). "Previous studies have shown that pro-inflammatory biomarkers, including IL-6, IL-10, IL-8, IL-15, CRP, TNF-α, and GDF-15, are associated with skeletal muscle decline and sarcopenia." (PMID 38026977, 2023).
sarcopenia (continued). "According to logistic regression analysis, sarcopenia was associated with age, erythrocyte sedimentation rate (ESR), C-reactive protein (CRP) (positively) and BMI, Iron (Fe), Total Cholesterol, albumin (%), albumin (g), and gamma proteins (negatively)." (PMID 37960189, 2023). "Regarding the biochemical parameters, the sarcopenia group had higher CRP levels (P <0.001) and lower serum phosphorus (P =0.033), serum magnesium (P=0.004), and albumin (P=0.002) levels." (PMID 37265691, 2023). "Age, alcoholic liver disease, C-reactive protein, sodium level, and controlling nutritional status score were extracted as factors contributing to sarcopenia (all p < 0.05)." (PMID 38024081, 2023). "In a meta-analysis including 1370 individuals, the authors reported that patients with sarcopenia had higher concentration of CRP compared with controls." (PMID 37488531, 2023). "The relationship between serum hypersensitive C-reactive protein levels and sarcopenia was only observed in men." (PMID 36615879, 2023). "Low-grade chronic inflammation, produced by slight elevations in circulating pro-inflammatory mediators (such as C-reactive protein (CRP), tumor necrosis factor (TNF), and IL-6), is among the causes of inducing sarcopenia." (PMID 38069224, 2023). "ESR and CRP were generally higher in female RA with sarcopenia, suggesting that disease activity was higher in the sarcopenic group, so sarcopenia was closely related to disease activity in RA itself." (PMID 35676311, 2022). "As a result of the multivariate analysis for PFS, sarcopenia (HR 2.08) and CRP > 6.5 mg/L (HR 2.57) were determined as an independent poor prognostic factors." (PMID 35575465, 2022). "Among the sarcopenia group, TSF and R-Leg-M were independent predictors of CRP, explaining 35% of the variances perceived (R2 = 0.35) in the sarcopenia group [(0.04(0.01), p = 0.005), (−0.15 (0.06), p = 0.025; respectively]." (PMID 36291982, 2022). "IL-6, TNF-α, and CRP levels have been reported to be significantly upregulated in patients with sarcopenia." (PMID 35162870, 2022). "This study showed that elevated CRP was more common in patients with sarcopenia (73.8% vs. 51.1%, p=0.029) and the coincidence of elevated CRP and adverse body composition features resulted in worse OS (p=0.008)." (PMID 36568174, 2022). "In a previous study including 99 CRLM patients, the same authors advocated a correlation between host-phenotype of adverse body composition features (sarcopenia, low visceral adipose tissue) and systemic inflammation (C-reactive protein >5 mg/mL)." (PMID 36568174, 2022). "After adjusting for age, BMI, hemoglobin, albumin, calcium, phosphorus, CRP, AMC, protein, and MIS, multivariate analysis showed that the TyG index was positively associated with sarcopenia (OR 9.97; 95% CI, 2.90–34.23; p < 0.001)." (PMID 36191303, 2022). "Sarcopenia together with an increased modified Glasgow prognostic score (mGPS) that contained CRP predicted dismal survival for patients developing locoregional Renal Cell Carcinoma." (PMID 36245530, 2022). "Previous studies on markers of sarcopenia have mostly focused on serum creatinine and cystatin C, but also on related inflammatory mediators such as C-reactive protein (CRP), tumor necrosis factor-alpha (TNF-α), and interleukins (IL)." (PMID 36046129, 2022). "Sarcopenia and a higher mGPS constituted by CRP were independently related to the dismal prognosis of cases having local renal cell carcinoma." (PMID 35747263, 2022). "A meta-analysis including 3072 sarcopenia cases and 8177 controls indicated that CRP levels were significantly elevated in people with sarcopenia." (PMID 35215488, 2022). "Multiple studies have shown that sarcopenia is associated with a significant increase in pro-inflammatory cytokines, including TNF-α, IL-6, and C-reactive protein." (PMID 36002808, 2022).
sarcopenia (continued). "Sarcopenia and the increased modified Glasgow prognostic score (mGPS) containing CRP were independently related to poor prognosis of cases showing local renal cell carcinoma (RCC)." (PMID 35215488, 2022). "In our study, in the multivariate analysis, sarcopenia maintained an independent correlation only with age, BMI, and CRP." (PMID 35884793, 2022). "The sarcopenia group had significantly higher C‐reactive protein (CRP), blood urea nitrogen, and haemoglobin A1c and had significantly lower total cholesterol and pulmonary function test results compared to those of the normal group (all P < 0.050)." (PMID 35170229, 2022). "CRP expression has been consistently related to sarcopenia, whereas the role played by GDF-15 still has to be clarified." (PMID 36499366, 2022). "In this study, sarcopenia and high CRP levels (systemic inflammation) were detected as independent risk factors on the PFS of erlotinib therapy." (PMID 35575465, 2022). "We found that high CRP level and sarcopenia were independent poor prognostic factors for PFS in patients with lung cancer using erlotinib." (PMID 35575465, 2022). "In line, a meta-analysis including 49 studies confirms that n-3 PUFA decreases the levels of IL-6 and CRP in middle-aged and older adults, thereby reducing the components of inflammageing, which contributes to sarcopenia." (PMID 35276842, 2022). "In general, patients with lower BMI, taller stature, higher CRP, higher PLT, lower PA, lower WBC, younger age, and lower ALB contributed to an increased risk of sarcopenia." (PMID 36612977, 2022). "The participants were classified into four groups based on their sarcopenia and CRP level status, both of which were determined to be poor prognostic factors for PFS, and median PFS of these groups were compared." (PMID 35575465, 2022). "Consistent with our results, variables associated with active inflammation such as CRP, PLT, and WBC were associated with a higher likelihood of sarcopenia." (PMID 36612977, 2022). "Inflammation is the driving mechanism in the pathophysiology of cancer sarcopenia, and different inflammatory markers are related to sarcopenia, such as C-reactive protein (CRP) and the neutrophil-to lymphocyte ratio." (PMID 35207557, 2022). "When CRP and IL-6 were additionally offered in the stepwise procedure, probable sarcopenia lost its significance." (PMID 36476473, 2022). "Sarcopenia (HR 2.08) and C-reactive protein > 6.5 mg/L (HR 2.57) were determined as independent poor prognostic factors for PFS of erlotinib therapy." (PMID 35575465, 2022). "With respect to laboratory variables, patients with sarcopenia had a higher CRP (p = 0.003) and lower hemoglobin (p < 0.001), WBC count (p = 0.002), albumin level (p < 0.001), and ALT (p = 0.013)." (PMID 34357140, 2021). "High levels of CRP have also been observed in sarcopenia patients in several cross-sectional studies." (PMID 33566325, 2021). "As blood biomarkers have been shown to be associated with the development of sarcopenia, this study will measure common blood biomarkers of IL-6, TNF-α, CRP, GH, IGF-1, and MSTN and FST as outcome measures." (PMID 34348792, 2021). "In 2017, a meta-analysis reported that patients with sarcopenia had significantly higher levels of C-reactive protein (CRP) compared to controls." (PMID 34198802, 2021). "HGS was significantly associated with baPWV for male (β = −0.11; P = 0.013) and female (β = −0.09; P = 0.011) with sarcopenia after adjustment for age, BMI, BP, HR, visceral fat, lipid profiles, CRP, smoking status, and medication used." (PMID 34887771, 2021). "Since the inflammation, oxidative stress and muscle structural integrity can affect the sarcopenia status, we next evaluated the correlations of the plasma 8-isoprostanes, CRP and CK levels with the selected panel of biomarkers." (PMID 33883602, 2021).
sarcopenia (continued). "Sarcopenia is considered the biological substrate for physical frailty and levels of the plasma inflammatory marker CRP are higher in patients with sarcopenia than in controls." (PMID 34277468, 2021). "Logistic regression was used to assess the associations of CRP and SII with sarcopenia and sarcopenic obesity." (PMID 34836213, 2021). "High levels of serum interleukin (IL)-6, C-reactive protein (CRP), and α1-antichymotrypsin (ACT) are associated with decreased muscle strength or muscle mass (muscular sarcopenia)." (PMID 34957015, 2021). "In particular, we observed that patient with altered CRP and sarcopenia had an 5.1 and 4.4 higher odds of reporting severe fatigue respectively, while patients with severe anxiety had an 3.7 higher risk of severe fatigue." (PMID 34315951, 2021). "As statistical significance was not consistently observed for CRP, future prospective cohort studies should consider measuring CRP longitudinally in order to further explore its relationship with sarcopenia and sarcopenic obesity." (PMID 34836213, 2021). "This study aimed to examine associations of C-reactive protein (CRP) and systemic immune-inflammation index (SII) with sarcopenia and sarcopenic obesity in older adults with chronic comorbidities." (PMID 34836213, 2021). "The levels of IL-6, TNFa and CRP have been reported to be significantly up-regulated in sarcopenia patients." (PMID 33921004, 2021). "Researchers found that patients with rheumatoid arthritis were more likely to suffer from sarcopenia based on age, BMI, C-reactive protein, and hip bone density." (PMID 34943268, 2021). "A meta-analysis compared inflammatory markers in participants with and without sarcopenia, and found that high-sensitivity C-reactive protein (hs-CRP) demonstrated a significantly positive correlation with sarcopenia." (PMID 34911470, 2021). "Development of sarcopenia has been previously associated with overexpression of pro-inflammatory factors, particularly IL-6, TNF-α, and C-reactive protein." (PMID 33375628, 2020). "The Glasgow Prognostic Score (based on the assessment of albumin and C-reactive protein (CRP) levels) or its modified version (including also complete blood count) can be used to distinguish cachexia and secondary sarcopenia." (PMID 32796600, 2020). "Accumulating evidence demonstrated that the serum levels of tumor necrosis factor (TNF)-α, interleukin (IL)-6, and C-reactive protein (CRP) are elevated in sarcopenia, typically up to 2–4-fold higher than those in young controls." (PMID 32498474, 2020). "Tumor necrosis factor-alpha, C-reactive protein, and interleukin-6 have been correlated with a decline in muscle mass and strength, suggesting a direct involvement in sarcopenia pathogenesis." (PMID 31947528, 2020). "Many inflammatory markers, such as interleukin- 6 (IL-6), C-reactive protein (CRP), and tumor necrosis factor α (TNF-α), have been linked with sarcopenia." (PMID 33160322, 2020). "In another cross-sectional study enrolled 3671 community-dwelling older adults, the PLR values were also positively correlated with CRP, and the elevations in PLR values were positively associated with sarcopenia status." (PMID 33160322, 2020). "Biological ageing is characterized by chronic inflammation while higher levels of CRP and IL-6 are considered to be predictors of age-related sarcopenia." (PMID 31717450, 2019). "Higher blood levels of C-reactive protein (CRP), IL-6, and TNF-α have been associated with an increased risk of osteoarthritis, dementia, sarcopenia, and aging." (PMID 29464019, 2018). "Our observation of increased IL-6 levels in sarcopenia is supported by several analyses, in which correlations between reduced physical performance and increased levels of IL-6 and C-reactive protein (CRP) levels have been reported." (PMID 30541467, 2018). "Sarcopenia is related to elevation in levels of inflammation markers, such as CRP, IL-621, and tumor necrosis factor (TNF)-α36." (PMID 30065297, 2018).
sarcopenia (continued). "In summary, our findings highlight an important role for CRP, IL-8 and other elements of immune function in the development of sarcopenia and its constituent components; muscle strength, muscle mass and physical function." (PMID 29101476, 2018). "Several clinical studies have measured serum CRP levels in an attempt to elucidate the role of inflammation in the pathogenesis of sarcopenia." (PMID 30115813, 2018). "Participants with sarcopenia tend to be older, male, to have higher body mass index (BMI), CRP, hemoglobin and RDW, and lower moderate-to-vigorous physical activity (MVPA)." (PMID 30065297, 2018). "We suggest additional studies be conducted to determine the CRP value to be used as a surrogate marker of sarcopenia." (PMID 27537502, 2016). "In the present study, we investigated the usefulness of sarcopenia as a prognostic biomarker to predict OS in advanced UC patients, along with known prognostic factors such as performance status (PS), anemia, CRP, and the presence of visceral metastasis." (PMID 25612215, 2015). "Sarcopenia was the strongest independent predictor of shorter OS (HR 3.36, P <0.001), along with higher CRP (HR 1.34, P = 0.001), upper urinary tract cancer (HR 2.13, P = 0.007), higher LDH (HR 2.12, P = 0.047), and higher ALP (HR 2.03, P = 0.048)." (PMID 25612215, 2015). "It is noteworthy that IL-6, TNF-α, CRP, and SAA have all been implicated in the pathogenesis of muscle atrophy in the context of sarcopenia or other muscle-wasting disorders." (PMID 25221511, 2014). "In contrast, the association between WBC and sarcopenia in our study diminished and disappeared after adjustment, suggesting that the relationship between WBC, CRP, and sarcopenia may be mediated by other factors, which were accounted for in our analysis." (PMID 40708651, 2025). "For the models of E-DII and inflammatory mediators, AUC measurements for E-DII + cfDNA (AUC = 0.805) were considered a good discrimination, and the evaluation was as acceptable for cytokines IL-1β, IL-6, TNFα and CRP (0.7 < AUC < 0.8) i.e., it enabled sarcopenia diagnosis." (PMID 41345186, 2025). "Among the four immune activation biomarkers, CRP showed a positive correlation with sarcopenia (SMD = 0.35, 95% CI (0.06, 0.64), K = 26, N = 8137, I2 = 96.0%) and the SO population (SMD = 1.71, 95% CI (0.2, 3.23), K = 7, N = 1154, I2 = 98.7%) compared to individuals with normal muscle function." (PMID 40507924, 2025). "Sarcopenia correlated with hemoglobin, albumin, CRP, and ESR." (PMID 40476129, 2025). "The secondary objectives were to find out whether there is any correlation between sarcopenia with CRP, ESR, albumin, and hemoglobin levels." (PMID 40476129, 2025). "This meta-analysis included 10 studies with a total of 754 patients and systematically evaluated the effects of acupuncture intervention on total efficiency, muscle mass, grip strength, usual gait speed, the 6-min walk test, SPPB, and C-reactive protein in sarcopenia patients." (PMID 41293592, 2025). "Thus, Fractions 5–7 were confirmed as high‐purity EVs‐enriched fractions and subsequently used to quantify sarcopenia‐associated markers, including adiponectin, myostatin, P3NP, CRP and TNF‐α, within plasma‐derived EVs using ELISA." (PMID 40162588, 2025). "Emerging evidence suggests that low-grade chronic inflammation—reflected by markers such as IL-6 and CRP—may contribute to the link between oral health and systemic conditions like frailty and sarcopenia." (PMID 40142799, 2025). "The secondary objectives were to find out whether there is any correlation of sarcopenia with C-reactive protein (CRP), erythrocyte sedimentation rate (ESR), albumin, and hemoglobin levels." (PMID 40476129, 2025). "Additionally, CRP levels were significantly higher in patients with sarcopenia (p < 0.001), suggesting increased inflammation." (PMID 41283022, 2025).